LRIF1 (ligand dependent nuclear receptor interacting factor 1)
Description:
Together with SMCHD1, involved in chromosome X inactivation in females by promoting the compaction of heterochromatin. Also able to repress the ligand-induced transcriptional activity of retinoic acid receptor alpha (RARA), possibly through direct recruitment of histone deacetylases. Also required for silencing of the DUX4 locus in somatic cells.
Synonyms: HBiX1; C1orf103; RIF1; FLJ11269; FSHD3
Tractability: PROTAC: UniProt records ubiquitination sites on it; ubiquitination databases record sites on it; its protein half-life has been measured.
Gene: Protein-coding gene on chromosome 1 (110,946,652 to 110,963,988, reverse strand). Ensembl gene ENSG00000121931.
Subcellular location: Chromosome; Nucleus matrix
Subcellular location (Human Protein Atlas): Nucleoplasm; Centriolar satellite
Gene Ontology:
Molecular function: protein binding; nuclear retinoic acid receptor binding
Biological process: dosage compensation by inactivation of X chromosome; regulation of DNA-templated transcription
Cellular component: Barr body; chromosome; chromosome, telomeric region; nuclear matrix; nucleoplasm
Genetic constraint (gnomAD): Loss-of-function variants: 32 observed, 55.82 expected, observed/expected ratio (o/e) 0.57, 90% interval 0.43 to 0.77. The upper end of that interval is the gene's LOEUF score, 0.77, which puts it in group 3 of 6, group 1 being the genes least tolerant of losing a copy. Missense variants: 886 observed, 938.78 expected, observed/expected ratio (o/e) 0.94, 90% interval 0.89 to 1. Synonymous variants: 323 observed, 335.87 expected, observed/expected ratio (o/e) 0.96, 90% interval 0.88 to 1.05.
Homologues: Orthologues: chimpanzee LRIF1 (99% identical), macaque LRIF1 (96% identical), dog LRIF1 (85% identical), pig LRIF1 (85% identical), rabbit LRIF1 (82% identical), mouse Lrif1 (69% identical), rat Lrif1 (67% identical), tropical clawed frog lrif1 (29% identical), zebrafish lrif1 (20% identical).
Diseases named in the same sentence as LRIF1 in open-access papers:
LRIF1 is named in the same sentence as 6 diseases in open-access papers, as found by Europe PMC text mining. Sharing a sentence is not in itself a finding about the gene and the disease. The quoted sentences say what the papers report.
facioscapulohumeral muscular dystrophy (2 papers, 2023 to 2025). An autosomal dominant disorder affecting the skeletal muscles of the face, scapula, and upper arm. "Here alternative modes of repression of D4Z4 by SMCHD1 and LRIF1 are identified, relevant for understanding facioscapulohumeral muscular dystrophy." (PMID 37380887, 2023).
leukemia (1 paper, 2021). A malignant (clonal) hematologic disorder, involving hematopoietic stem cells and characterized by the presence of primitive or atypical myeloid or lymphoid cells in the bone marrow and the blood. "In addition, we identified genes of previously unknown cancer relevance with regards to leukemia circulation (e.g., LRIF1, DNAJC1, and CMC2) and therapeutic treatment (e.g., EBPL, MESDC2, ZRANB2, GTF2A2)." (PMID 34764253, 2021).
tumor (3 papers, 2016 to 2025). "In a detailed examination of 114 paired samples from the TCGA–LUAD cohort, significant variations were observed in the expression of LRIF1, STK26, TNS2, and TTF2 between tumor and normal tissues, with p values less than 0.001." (PMID 40212965, 2025). "Expression levels of the key genes TNS2, LRIF1, STK26, and TTF2 showed marked differences, exhibiting substantially elevated expression in tumor tissues versus normal tissues." (PMID 40212965, 2025).
cancer (2 papers, 2021). A tumor composed of atypical neoplastic, often pleomorphic cells that invade other tissues. "Three genes ARID2, LRIF1 and UBE2L6 were not covered by any representative term with only ARID2 being an NCG cancer gene." (PMID 34504716, 2021).
LRIF1 also shares sentences with these, for which no sentence is quoted: epilepsy (1 paper); neurodevelopmental disorder (1).